CXCL10 (C-X-C motif chemokine ligand 10)
Diseases named in the same sentence as CXCL10 in open-access papers (continued):
Sharing a sentence is not in itself a finding about the gene and the disease.
COVID-19 (continued). "In the present study, all COVID-19 patients exhibited significantly higher levels of IL-6, CXCL-10, HGF, MIG, MCP-1, and G-CSF than the non-COVID-19 respiratory disease controls." (PMID 37685858, 2023). "Subsequently, Paxlovid was analyzed against the core targets of LUAD/COVID-19 (CXCL2, CCL2, IL12B, CSF3, LBP, IL6, CXCL10) and Paxlovid, and the results showed that IL-6, IL12B, LBP and Paxlovid could be combined." (PMID 36157452, 2022). "In addition to displaying correlations with immune cell frequencies in the airways, the chemokines CXCL9, CXCL10, and CXCL11, and their receptor, CXCR3, are all members of the red WGCNA module that characterized the post-COVID-19 airway." (PMID 35151371, 2022). "Results showed that compared with patients with less severe infections without Intensive Care Unit (ICU), patients with COVID-19 with ICU had higher concentrations of CXCL10, CCL2, and TNF-α." (PMID 35911765, 2022). "Severe COVID-19 patients showed impaired IFN-1 signaling compared to mild patients, and developed an inappropriate inflammatory state due to early delay in IFN-1 expression and activation of pro-inflammatory cytokines (IL-1, IL-6, IL-8, MCP-1, and CXCL-10)." (PMID 35185933, 2022). "Thus, in the case of both PRAD and COVID-19, TMPRSS2 and CXCL10 can be considered as two prominent biomarkers." (PMID 36239108, 2022). "Monocytes producing ligands for CXCR3 have been shown to be expanded in the lungs of COVID-19 patients, and although not significant, CXCL10 mRNA expression was increased in monocytic macrophages from BAL fluid from COVID-19 patients with moderate disease." (PMID 35371005, 2022). "Knowing that CXCL10, on which this review focuses on, is one of the most important factors that amplify the immune response through the requirement of Th1 cells, thus, it was suggested that PDE4 inhibitors are a promising therapeutic option for COVID-19." (PMID 35409036, 2022). "In COVID-19 patients, SARS-CoV-2 infection triggered excessive production of CXCL10, thereby resulting in over recruitment of inflammatory neutrophils, macrophages and Th1 lymphocytes into lung tissue which could cause pulmonary inflammation and destruction." (PMID 36426362, 2022). "Changes in chemokine levels in peripheral blood of COVID-19 and influenza patients have been addressed by multiple studies, in particular CXCL9, CXCL10, CXCL11, CXCL16, CCL2, and CCL5 were altered in patients as compared to controls, and levels correlated to disease severity." (PMID 35371005, 2022). "Additionally, IL-4, IL-12, IL-2, CXCL10, platelet derived growth factor subunit A (PDGFA), and IFN-α2a kinetic changes were similar between the natural course of early COVID-19 and inhaled budesonide." (PMID 35397798, 2022). "The immunological feature of severe COVID-19 could be defined by the “core signature” cytokines in cluster 2: MCP-3, IL-6, IFN-γ, and CXCL10, which strongly correlated with each other and CRP, and are involved in cytokine release storm." (PMID 35350784, 2022). "In fact, from the group comparison of COVID-19 vs. non-COVID-19, the authors identified 14 specific inflammatory proteins that can be related to SARS-CoV-2 infection, namely CXCL5, CXCL10, CXCL11, Gal-9, IL-18, IL-18R1, IFNγ, LIF-R, MCP-2, MCP-3, MERTK, MMP-1, PD-L1, and TNF." (PMID 35269564, 2022). "However, in a univariate analysis, TGF-β, CXCL-10, IFN gamma, and IL-7 affected mortality in COVID-19 patients." (PMID 36286038, 2022). "However, in univariate analysis, the cytokines TGF-β, CXCL-10, IFN gamma, and IL-7 significantly affected mortality in COVID-19 patients." (PMID 36286038, 2022). "It is, therefore, not surprising that the determination of the serum CXCL10 levels has been performed in patients with COVID-19." (PMID 35336843, 2022).
COVID-19 (continued). "While baseline secretion of proinflammatory cytokines was massively elevated, whole blood from COVID-19 patients elicited diminished release of T-cellular (e.g., IFN-γ, IL-2) and innate immune cell-derived (e.g., CXCL9, CXCL10) cytokines in response to A. fumigatus and R. arrhizus antigens." (PMID 36052094, 2022). "It has been hypothesized that a decreased CXCL-10 profile in individuals with FXS would indicate a protective effect against cytokine release and Cytokine Storm Syndrome in COVID-19 patients." (PMID 35632654, 2022). "Findings from mouse models, cellular systems, and samples from patients with SARS-CoV-2-induced COVID-19 have shown massive generation of C5a, CCL chemokines (e.g., CCL2, CCL3, and CCL5), CXCL chemokines (e.g., CXCL9 and CXCL10), and growth factors, i.e., TGFβ, GCSF, GMCSF, VEGF, FGF, and PDGF." (PMID 36430817, 2022). "Transcriptome analysis of BALF samples indicated that the levels of pro-inflammatory chemokines such as CXCL1, CXCL2, CXCL6, CXCL8 (IL-8), CXCL10 (IP-10), CCL2 (MCP-1), CCL3 (MIP-1A), and CCL4 (MIP-1B) are elevated in patients with COVID-19, which correlated with disease severity." (PMID 36111104, 2022). "However, an early but transient inflammatory cytokine response with increased CXCL10, IFN-g, IP-10/, IL-6 and CRP was observed at day 2 and returned to baseline levels by day 8 following a COVID-19 vaccination with BNT162b2 mRNA (Pfizer/BioNtech)." (PMID 34835155, 2021). "NDG from severe/critical COVID-19 patients may be primed in vivo to spontaneously produce NETs, since they are exposed to IL-6, IL-2, IL-7, TNF, CXCL10, MCP-1, MIP1a, GM-CSF and M-CSF during the cytokine storm." (PMID 34685525, 2021). "Our data demonstrated strong enrichment of CCL2/19/20, CXCL10, GM-CSF, IL-6/8/15, S100A9, SCGF, TNF and TREM-1 in COVID-19, which could potentially play a critical role on the pathogenesis of the disease." (PMID 34238349, 2021). "Subsequently, to further determine whether SARS-CoV-2 infection in AAV/hACE2 mice model could also induce proinflammatory mediators as shown in severe COVID-19 patients, RNA levels of TNF-α, IL-1β, IL-6, CCL2, and CXCL10 in mice lung homogenates were measured." (PMID 34379705, 2021). "Moreover, a significant correlation between COVID-19 severity and the serum concentrations of IL-1, IL-2, IL-6, IL-7, IL-10, TNF-α, G-CSF, CCL2, CCL3, CXCL8, and CXCL10 has been observed." (PMID 34209845, 2021). "In particular, we have identified a CXCL10+ CCL2+ inflammatory macrophage phenotype shared between tissues affected in autoimmune disease (RA), inflammatory diseases (CD and UC), and infectious disease (COVID-19)." (PMID 33879239, 2021). "Levels of inflammatory cytokines/chemokines, including Eotaxin, G-CSF, Gro-α, CXCL-10, RANTES (CCL5), IL-2Rα, MCP-1, and SCGF-b, were found to be highly elevated in plasma samples from COVID-19 patients within a week post-symptoms as compared to healthy controls." (PMID 34242356, 2021). "Targeted proteomics to measure abundance levels of MX1, ISG15, STAT1, RIG-I, and CXCL10 detected proteomic signatures of interferon-mediated antiviral signaling that differentiated COVID-19-positive from COVID-19-negative cases." (PMID 34400346, 2021). "The identified crucial cytokine panel, including IL6, IL1β, IL10, CXCL10, IGF1, and GALECTIN-1, may offer the selective targets to improve the efficacy of COVID-19 therapy." (PMID 34238338, 2021). "Clinical studies have shown elevated inflammatory cytokines, including tumor necrosis factor-alpha (TNF- α), interleukins (IL; IL2, IL6, IL7, IL8, IL9, and IL10), chemokines (CXCL10, CCL2, IP10, MCP1), and colony-stimulating factors (G-CSF, GM-CSF) in COVID-19 patients compared to a healthy person." (PMID 34513735, 2021).
COVID-19 (continued). "The analysis of the plasmatic levels of inflammatory chemokines and cytokines in patients with COVID-19 and MIS-C showed higher levels of IL-6, CXCL8, CCL2/MCP-1, CXCL9/MIG, and CXCL10/IP-10 in MIS-C, whereas CCL5 levels were significantly higher in the COVID-19 group." (PMID 33841438, 2021). "PIMS-TS children had significantly elevated levels of cytokines, IFNγ, IL-2, TNFα, IL-1α, IFNα, IFNβ, IL-6, IL-15, IL-17A, GM-CSF, IL-10, IL-33 and IL-Ra; elevated chemokines, CCL2, CCL19, CCL20 and CXCL10 and elevated VEGF, Granzyme B and PDL-1 in comparison to COVID-19, seropositive and controls." (PMID 33813138, 2021). "Moreover, the fatality rate was found positively correlated with CXCL10 and CCL2 critically ill patients with COVID-19." (PMID 33946736, 2021). "Studies have shown that several circulating cytokines and chemokines such as TNFα, CXCL-10, IL-6, and IL-8 are differentially expressed during SARS-CoV-2 infection, and this cytokine/chemokine storm likely contributes to the poor prognosis of COVID-19." (PMID 34531741, 2021). "In this study, we built a single-cell immune reference from multiple inflamed disease tissues and identified two inflammatory macrophage states, CXCL10+ CCL2+ and FCN1+ inflammatory macrophages, that were shared between COVID-19 and inflammatory diseases such as RA, CD, and UC." (PMID 33879239, 2021). "Of note, the levels of CXCL10 were significantly correlated with classical markers only in COVID-19 survivors not transferred to the ICU." (PMID 34663207, 2021). "Importantly, our meta-analysis identified 4 potential novel targets (CCL20, CSF3, CXCL1, CXCL10) associated with COVID-19 pathogenesis, targeted by 6 existing drugs that have not been studied in clinical trials for treatment of COVID-19 and could be repurposed." (PMID 34582497, 2021). "To investigate the role of cytokines and chemokines in the inflammatory status of COVID-19 and MIS-C, we measured plasma levels of IL-1ß, IL-2, IL-4, IL-5, IL-6, IL-10, TNF-α, IL-17A, IFN-α, IFN-γ, CXCL10/IP-10, CXCL8/IL-8, CXCL9/MIG, CCL5/RANTES, and CCL2/MCP1." (PMID 33841438, 2021). "CXCL10 is an interferon (IFN)-inducible chemokine and represents a biomarker for the SARS-CoV-2 cytokine storm, providing a correlate of disease severity in COVID-19 patients." (PMID 34876520, 2021). "IL-6, CXCL10, CXCL9, CCL2, IL1-Ra, IL-10, G-CSF and TNF-α were the cytokines with the highest contribution to dimension 2 in the PCA and were significantly increased in acute COVID-19 patients in comparison to HC." (PMID 34572439, 2021). "A single-cell study of bronchoalveolar lavage fluid (BALF) in intubated COVID-19 patients identified two inflammatory macrophage subsets—one characterized by CCL2, CCL3, and CXCL10 expression and a second by FCN1 and S100A8—as potential mediators of pathology in this late-stage disease." (PMID 33879239, 2021). "Comparative proteomics identified statistically robust overexpression of several inflammatory cytokines, specifically IL6, IL18, CCL7, CXCL10, and CXCL11, which could be targeted to prevent untoward immune-inflammatory effects in COVID-19 patients." (PMID 35145507, 2021). "Recent research has also identified that the synergism of TNF-α and IFN-γ can trigger inflammatory cell death, tissue damage, and mortality in SARS-CoV-2 infection, and shown increased levels of IFN-γ, TNF-α, CXCL10, and CCL2 in the serum of severe COVID-19 patients." (PMID 33879239, 2021). "The MCODE plugin in Metascape was used to determine important modules and related hub genes in the constructed PPI network, and chemokines such as CCR1, CCL19, CXCL10, and CXCL16 were identified to present the most obvious changes in COVID-19 disease progression." (PMID 33195212, 2020).
COVID-19 (continued). "And the subsequent PPI analysis results in our study also confirmed that chemokines related to inflammatory responses, such as CCR1, CCL19, and CXCL10, and the immune response-related gene FPR1 presented significant expression changes in the progression of COVID-19." (PMID 33195212, 2020). "The cytokine storm landscape of COVID-19 patients was further demonstrated in a retrospective study showing higher concentrations of IL-2, IL-7, IL-10, G-CSF, C-X-C motif chemokine ligand (CXCL)-10, C-C motif chemokine ligand (CCL)-2, CCL-3, and TNF-α in the plasma of severe COVID-19 patients." (PMID 33584335, 2020). "Thus, CXCL10 is a promising surrogate marker for potentially diagnosing poor SARS-CoV-2-specific CD4+ and CD8+ T cell responses in patients with acute COVID-19." (PMID 33010815, 2020). "Consistently, in this study we found the expression of a large number of cytokines are significantly elevated in COVID-19 patients BALF samples compared to control, including pro-inflammatory cytokines CXCL1, CXCL2, CXCL6, CXCL8, CXCL10/IP-10, CCL2/MCP-1, CCL3/MIP-1A and CCL4/MIP1B." (PMID 32228226, 2020). "Cytokine storm is hypercytokinemia that increases the volume of pro-inflammatory cytokines in the serum (e.g. IL-1β, IL-6, IL-12, INF-γ) and chemokines (CXCL10 and CCL2), and is correlated with pulmonary inflammation and extensive lung involvement as seen in COVID-19 patients." (PMID 33205807, 2020). "PBMCs derived from COVID-19 patients and stimulated in vitro showed an increase in expression of CCL2, CXCL10, Eotaxin, and IL-1RA, and stimulation of CD8+ T cells were associated with an increase in IFN-γ levels, which indicates the functional responsiveness of these cells." (PMID 33335518, 2020). "Here, we show that airway epithelial cells have a restricted cytokine release profile in response to SARS-CoV-2 infection and are unlikely to be the source of these cytokines elevated in COVID-19 patient serum, with the exception of CXCL10." (PMID 33284849, 2020). "COVID-19 ARDS patients had significantly higher plasma concentrations of CCL5 (p = 0.025) and non-significantly higher plasma concentrations of CXCL2 (p = 0.094), CXCL10 (p = 0.287), CD40 ligand (p = 0.125), IL-10 (p = 0.232), and GM-CSF (p = 0.332) compared with non-COVID-19 ARDS patients." (PMID 33138839, 2020). "Elevated levels of TNF-α, CXCL10, CCL2, and IL-10 in COVID-19 patients correlate with reduced populations of specific intestinal bacterial, which suggests that gut dysbiosis may contribute significantly to the development of intense and widespread inflammation." (PMID 38701071, 2024). "In conclusion, CNS immune-mediated adverse events of COVID-19 vaccination appear to be very rare and consist mostly of Ab-negative AE, myelitis, and ADEM developing approximately 2 weeks after vaccination, when a mounting robust CD8+ T cell response is suggested by the increased CXCL10 CSF levels." (PMID 38375477, 2024). "First we compared the soluble proteome from aIFNpos COVID-19 patients to healthy individuals and observed a significant inflammatory response in aIFNpos patients with drastically elevated levels of proteins such as interleukin 6 (IL-6), IFN-γ, CXCL10, and CCL7." (PMID 38421006, 2024). "Our preclinical model results do not support targeting CXCL10 therapeutically in severe COVID-19." (PMID 39803542, 2024). "However, in older COVID-19 patients more and stronger correlations could be detected with hs-CRP (all p < 0.01): IL8 (r = 0.548), MCP3 (r = 0.720), CXCL10 (r = 0.460), CCL23 (r = 0.577) and IL6 (r = 0.706)." (PMID 37832397, 2023). "Among prominent ones are CXCL10, a marker of acute viral infection, ISG15, both an extracellular cytokine and an intracellular protein modifier, IFI6 that may be involved in the regulation of cell apoptosis and IFI27, a proven predictor for COVID-19 outcomes." (PMID 37685932, 2023).
COVID-19 (continued). "MiRNAs that were downregulated in serum of COVID-19 patients mainly target genes promoting angiogenesis (e.g., VEGFA, ANGPT2, COL4A1, FGF2, ZEB1), apoptosis, autophagy, stress response (e.g., ATG12, ATG14, ATG2B, SOD2, TXNIP), and inflammation (e.g., CXCL9, CXCL10, IL1R1, TNF)." (PMID 36032130, 2022). "Compared to the healthy controls, patients with COVID-19 had significantly higher circulating concentrations of 19 inflammatory mediators, namely interleukins 1α, 2, 6, 7, 8, 10 and 15, CRP, SAA, ICAM-1, VCAM-1, CXCL10, CCL3, CCL26, IFN-γ, TNF-α, bFGF, PlGF and Flt-1 (P < 0.05)." (PMID 35958594, 2022). "Studies focusing on single-cell RNA sequencing of COVID-19 patient bronchoalveolar lavage fluid pointed out that macrophage subsets producing CCL2 and CXCL10 are abundant in the bronchoalveolar lavage fluid from severe COVID-9 patients and might be potential mediators in the COVID-19 disease." (PMID 36451835, 2022). "Although this study analyzed a large number of biomarkers (71biomarkers) and suggested a correlation of some with the severity of COVID-19, we did not analyze other markers associated with the severity of COVID, such as CHI3L1 and IGFALS59, CXCL8, CXCL10, and CCL2060." (PMID 36163447, 2022). "Significant levels of macrophage chemo-attractants such as CXCL10 and CCL2/MCP-1, as well as neutrophil chemo-attractants like CXCL2 and CXCL8, enhance immune cell migration to the site of infection, which is consistent with mononuclear cell infiltrates in COVID-19 patients’ lung tissues." (PMID 35958594, 2022). "Moreover, there were 16 kinds of CCGFs, including HGF, CXCL8/IL-8, CCL7/cP-3, CCL2/McP-1, CXCL9/MIG, CXCL10/IP-10, IL-6, IL-18, IL-2, M-CSF, IL-1Rα, IL-2Rα/CD25, IFN-γ, CC L3/MIP-1α, FGF, and SCF which were abnormally elevated in patients who died from COVID-19." (PMID 35528178, 2022). "We found that severe COVID-19 patients displayed, as extensively already reported, high level of circulating inflammatory cytokines, including IL-6, TNF-α, IL-1β and chemokines such as CXCL-10, CCL-2 and CXCL-8 contributing to the diffuse inflammatory status and the so-called cytokine storm." (PMID 34473805, 2021). "Transcriptomic studies revealed remarkably enhanced expressions of CCL2, CXCL8, CSF3, CSF2, and CXCL10 in Calu-3 cells infected with SARS-CoV-2, inflammatory factors that were shown to be strongly elevated in the serum of patients with severe clinical symptoms of COVID-19." (PMID 34578229, 2021). "While CXCL9, CXCL10 and CXCL11 expression levels were increased both in moderate and severe disease compared to healthy levels, IL1β, IL6, TNF as well as CCL2, CCL3, CCL4 and CCL7 were expressed at higher levels in lung macrophages from patients with severe COVID-19." (PMID 34367190, 2021). "Moreover the role of microbiota in modulating host immune response, and potentially influencing disease severity also in COVID-19, is confirmed by the inverse correlation of bacterial species depleted in COVID-19 patients, with plasma concentration of several cytokines (IL10, TNF-α, CXCL10, CCL2)." (PMID 34070662, 2021). "Notably, we observed a significant correlation between the cross-disease shared CXCL10+ CCL2+ macrophages and two monocyte-derived alveolar macrophage (MoAM) inflammatory phenotypes from this independent severe COVID-19 cohort (wherein they were referred to as MoAM1 and MoAM2)." (PMID 33879239, 2021). "Thus, adipose IRF5 transcripts in obesity correlate positively with TNF-α, IL-1β, IL-6, CXCL8/IL-8, CXCL9/MIG, CXCL10/IP10, CCL2/MCP1, CCL5, and CCL7/MCP3, all of which can be elevated in COVID-19 “cytokine storm”; positive correlations with IL-2 and IL-12 have been reported by the same group." (PMID 33936053, 2021).